STEAP1 (STEAP family member 1)
Diseases named in the same sentence as STEAP1 in open-access papers (continued):
Sharing a sentence is not in itself a finding about the gene and the disease.
breast carcinoma (15 papers, 2016 to 2024). "Low expression; Associated with good prognosis; STEAP1 and STEAP2 inhibit the invasion, proliferation, and metastasis of breast cancer by inhibiting EMT." (PMID 39676279, 2024). "In breast cancer, STEAP1 and STEAP2 inhibit EMT by inhibiting EMT‐related genes and the PI3K/AKT/mTOR signaling pathway to impede cell proliferation, invasion, and metastasis." (PMID 39676279, 2024). "STEAP1 expression is downregulated in breast cancer tissues compared to normal cells, and low STEAP1 expression is associated with poor prognoses in patients with breast cancer." (PMID 37909017, 2023). "While STEAP3 was unrelated to any improvement in overall breast cancer patient OS, other studies have found a relationship between downregulation of the related STEAP1, STEAP2, and STEAP4 proteins and improved outcomes." (PMID 37064114, 2023). "STEAP1 plays an integral role in the cell junctions and performs a tumor suppressor function in endometrial carcinomas, breast cancers and gastric cancer." (PMID 33535185, 2021). "The relative RNA expression of STEAPs in breast tissues and breast cancer was analyzed accordingly and found that STEAP1/2/4 were highly expressed in normal mammary glands compared with that in breast cancer tissues." (PMID 32802887, 2020). "Survival analysis revealed that breast cancer patients with high levels of STEAP1, STEAP2, and STEAP4 had a good prognosis, while those with low expression had high overall mortality." (PMID 32802887, 2020). "Studies have shown that the downregulation of STEAP1 expression in breast cancer enhances the invasion and migration of cells and increases the expression of EMT-related biomarkers." (PMID 32802887, 2020). "Kaplan–Meier analysis previously revealed that breast cancer patients with low STEAP1 expression levels tended to have a poor prognosis." (PMID 32265985, 2020). "A positive relationship between the STEAP1 mRNA level and the overall survival (OS) in breast cancer was found (p = 0.006)." (PMID 32802887, 2020). "In the current study, it is found that the expression of STEAP1 in breast cancer was lower than that in normal breast epithelium." (PMID 32802887, 2020). "In contrast, STEAP1 exerts tumor suppressive effects on breast cancer cells." (PMID 37909017, 2023). "Therefore, interventions to inhibit STEAP1 can be useful as antimetastatic drugs for breast cancer." (PMID 37909017, 2023). "STEAP proteins include STEAP1‐4 and atypical STEAP1B; among them, STEAP1‐4 is lower expressed in breast cancer compared with normal tissues, and some people believe that STEAP1‐4 is a tumor suppressor of breast cancer." (PMID 39676279, 2024). "This can be attributed to EMT suppression by STEAP1 through CDH1 upregulation and the downregulation of EMT-related genes in breast cancer cells." (PMID 37909017, 2023). "The current study also predicted the participation of STEAP1 and STEAP2 in the process of mineral absorption through converting Cu2+ to Cu+ and promoting copper absorption, which may be the underlying mechanism that STEAPs are involved in the development of breast cancers." (PMID 32802887, 2020). "STEAP1, STEAP2, and STEAP4 are predicted to be the potential prognostic biomarkers for breast cancer patients, providing novel therapeutic strategies for them." (PMID 32802887, 2020). "STEAP1 upregulation significantly inhibited the capacity of migration of the tumor cells and the invasion potential and downregulated the expression of EMT-related genes in human breast cancer." (PMID 37999477, 2023). "Moreover, STEAP1 was downregulated in breast cancer tissues and negatively correlated with the TNM stage, tumor grade, and lymph node metastasis in breast cancer patients." (PMID 32265985, 2020). "The results from ONCOMINE showed downregulation of STEAP1, STEAP2, and STEAP4 in breast cancers." (PMID 32802887, 2020).
breast carcinoma (continued). "Moreover, STEAP1, STEAP2, and STEAP4 are related to the prognosis of breast cancer patients, providing an important theoretical basis and clinical guidance for the development of therapeutic targets and drugs for breast cancer patients." (PMID 32802887, 2020). "Furthermore, as evident from S7B–S7D Table, several late-type genes showed a significant, but opposite, association with prognosis in one or more cohorts compared to the initial analysis of breast cancer, exemplified by RPL10, EIF4B, GPBP1L1 in NSCLC and RPL3, RPS6 and STEAP1 in ovarian cancer." (PMID 27926932, 2016).
gastric cancer (10 papers, 2018 to 2023). A primary or metastatic malignant neoplasm involving the stomach. "This was an unexpected finding since a previous study showed that the downregulation of STEAP1 significantly increased the chemosensitivity of gastric cancer cells to docetaxel treatment." (PMID 37047621, 2023). "STEAP1 has been studied in a variety of cancers, such as breast, prostate, and stomach cancers, and has been shown to play a role in tumorigenesis and tumor inhibition." (PMID 35346237, 2022). "In gastric cancer, expression of STEAP1 has been shown to promote proliferation, migration, invasiveness, and tumorigenicity." (PMID 36216827, 2022). "This study aimed to clarify the role of STEAP1 in gastric cancer tumour growth and metastasis, as well as its molecular mechanism of action.Statistical methods were used for clinical data analysis." (PMID 33128353, 2020). "We initially determined STEAP1 protein expression in metastatic gastric cancer tissue samples and normal adjacent controls using immunoblot analysis." (PMID 31949502, 2020). "STEAP1 plays a role as an oncogene in gastric cancer, and this result was consistent with the conclusion that STEAP1 is an oncogene in other kinds of cancer." (PMID 33128353, 2020). "The goal of the present study was to understand how of STEAP1 expression in gastric cancer patients is regulated." (PMID 31949502, 2020). "The GEPIA database showed that the STEAP1 gene was more highly expressed in gastric cancer than in the normal tissue." (PMID 33128353, 2020). "In our study, we will discuss the influence of STEAP1 on the proliferation, invasion and inflammatory reactions in gastric cancer." (PMID 33128353, 2020). "In our study, STEAP1 was overexpressed in gastric cancer and closely related to the prognosis of patients." (PMID 33128353, 2020). "RNAi-mediated silencing of STEAP1 potentiated chemosensitivity of the MKN45 cells to docetaxel treatment, highlighting the importance of STEAP1 as a novel biomarker in gastric cancer patients with peritoneal metastasis." (PMID 30246786, 2018). "Taken together, these data suggest that high expression of STEAP1 is required for gastric cancer formation and progression." (PMID 30246786, 2018). "STEAP1 is thus induced translationally and its expression promotes proliferation, migration, invasiveness, and tumorigenicity of gastric cancer." (PMID 30246786, 2018). "In conclusion, STEAP1 was overexpressed in gastric cancer and closely connected with OS." (PMID 33128353, 2020). "In the results,we found STEAP1 was overexpressed in gastric cancer tissues and cell lines." (PMID 33128353, 2020). "Thus, given its high tumor specificity and membrane-bound localization, STEAP1 is an attractive candidate for targeted therapy in gastric cancer patients with peritoneal metastasis." (PMID 30246786, 2018). "STEAP1 has also been classified as a mesenchymal stem cell marker, supporting the relationship we observed with peritoneal metastasis of gastric cancer." (PMID 30246786, 2018).
lung adenocarcinoma (8 papers, 2020 to 2025). A carcinoma that arises from the lung and is characterized by the presence of malignant glandular epithelial cells. "In lung adenocarcinoma, STEAP1 is reported to be involved in processes closely associated with cancer cell proliferation, such as cell division, cytokine production, cytokine signaling, and DNA replication." (PMID 34527572, 2021). "Previous studies have shown that STEAP1 expression is upregulated in lung adenocarcinoma cells, where it regulates cellular epithelial–mesenchymal transition (EMT) through the (JAK2/STAT3) signaling pathway." (PMID 39991151, 2025). "LAMC2 and STEAP1 been demonstrated to enhance the migration and invasion of lung adenocarcinoma cells, concomitant with the induction of epithelial-mesenchymal transition (EMT)." (PMID 40808964, 2025). "For lung adenocarcinoma, the level of STEAP1 and STEAP2, which have the ability to reduce Fe(3+) to Fe(2+) and stimulate the cellular iron uptake, were negatively related to prognosis of patients based on multiple databases." (PMID 38602575, 2024).
bladder cancer (7 papers, 2004 to 2025). "The four prostate and bladder cancer cell lines LNCaP, C4-2B, 22Rv1, and UM-UC-3, which are all known to express STEAP1,17,22,29,30 displayed robust mAb staining." (PMID 35860008, 2022). "Furthermore, the upregulation of STEAP1 has been also detected in lung, gastric, colorectal, renal, and bladder cancer." (PMID 32802887, 2020). "STEAP1 is overexpressed in wide variety of cancers including prostate and bladder cancer." (PMID 30246786, 2018).
colorectal cancer (6 papers, 2016 to 2025). A primary or metastatic malignant neoplasm that affects the colon or rectum. "STEAP1 has been shown to be overexpressed in a number of tumour types, while elevated levels of STEAP1 were associated with poor survival in colorectal cancer, DLBCL, multiple myeloma and AML." (PMID 32992503, 2020). "The aim of this study was to investigate the possible association of STEAP1 expression with colorectal cancer prognosis." (PMID 27104516, 2016). "Similarly, STEAP1 overexpression is linked to poorer overall survival (OS) in colorectal cancer, diffuse large B-cell lymphoma, acute myeloid leukemia, and multiple myeloma." (PMID 40299363, 2025). "Interference of STEAP1 inhibited proliferation but promoted apoptosis and increased the production of reactive oxygen species (ROS) in colorectal cancer cells." (PMID 32265985, 2020). "The present investigation therefore explored the possibility of a potential prognostic role for STEAP1 in colorectal cancer." (PMID 27104516, 2016). "The present study therefore investigated the potential usefulness of STEAP1 in the prognosis of colorectal cancer patients." (PMID 27104516, 2016). "We verified a role for STEAP1 in colorectal cancer patients by evaluating its expression in primary tumors from 165 patients." (PMID 27104516, 2016). "Further investigation of the possible mechanism of STEAP1 in colorectal cancer is necessary to identify the role of STEAP1 among different cancer types." (PMID 27104516, 2016). "We used the Cox regression model to evaluate the prognostic role of age, gender, stage, and STEAP1 expression in colorectal cancer patients." (PMID 27104516, 2016). "The present study demonstrates the feasibility of using STEAP1 to predict the prognosis of colorectal cancer patients." (PMID 27104516, 2016). "We verified a prognostic role for STEAP1 expression in colorectal cancer by collecting overall survival data from 165 patients." (PMID 27104516, 2016). "STEAP1 expression was analyzed by immunohistochemical staining of a tissue array of 165 cancer specimens from primary colorectal cancer patients." (PMID 27104516, 2016). "STEAP1 overexpression is detected in different cancer types and was associated with a poorer prognosis for AML, multiple myeloma, diffuse large B cell lymphoma, and colorectal cancer." (PMID 32817744, 2020). "We recently found STEAP1 overexpression at the RNA level in circulating tumor cells of colorectal cancer, which suggested that STEAP1 might have a role in tumor metastasis." (PMID 27104516, 2016). "A prognostic role has not been previously demonstrated for STEAP1 in colorectal cancer." (PMID 27104516, 2016). "However, the prognostic role of STEAP1 is still controversial, and no role for STEAP1 has yet been indicated in colorectal cancer." (PMID 27104516, 2016). "In addition, no study has yet provided evidence for a role for STEAP1 in colorectal cancer." (PMID 27104516, 2016).
lung carcinoma (6 papers, 2020 to 2023). "Several groups have reported that STEAP1 is significantly upregulated in lung cancer compared to the normal cells and is associated with poor prognoses." (PMID 37909017, 2023). "Furthermore, knockdown of STEAP1 using siRNA reduced endothelial cell migration and tube formation, which implicated STEAP1 as a novel vascular target in lung cancer." (PMID 37909017, 2023). "Compared with normal lung tissue and epithelial cells, the expression of STEAP1 in lung cancer tissue was upregulated." (PMID 35346237, 2022). "Considering the possible association between STEAP1 and STEAP2, STEAP1 and STEAP2 seem to be significantly co-expressed in 59 cancer cell lines, but are significantly negatively correlated in lung cancer." (PMID 35346237, 2022). "Compared with the recognized classical markers of lung cancer, STEAP1 and STEAP2 have obvious advantages." (PMID 35346237, 2022). "STEAP1 expression was upregulated in nine different types of human cancers, including prostate and lung cancer, compared to normal tissues." (PMID 35346237, 2022). "Immunohistochemical analysis showed that STEAP1 protein expression was significantly upregulated in lung cancer compared to that in adjacent tissues." (PMID 35346237, 2022). "The expression of STEAP1 was positively correlated with the migration and invasion abilities of lung cancer cells." (PMID 35346237, 2022). "This study showed that STEAP1 protein overexpression was significantly correlated with poor prognosis of lung cancer, and STEAP2 protein downregulation was significantly correlated with poor prognosis of lung cancer." (PMID 35346237, 2022). "In this study, we found through an online database that STEAP1 expression level was significantly upregulated in lung cancer tissue, and high STEAP1 expression was positively correlated with poor prognosis." (PMID 35346237, 2022). "STEAP1 expression was related to the pathological stage, lymph node metastasis, and histological grade of lung cancer, and the expression of STEAP1 gradually increased with the enhancement of the invasion ability of lung cancer cells." (PMID 35346237, 2022). "Collectively, STEAP1 appears to be a promising biomarker and therapeutic target in lung cancer." (PMID 37909017, 2023). "Oncomine results showed that STEAP1 expression was upregulated in lung cancer." (PMID 35346237, 2022). "STEAP1 and STEAP2 are expected to be potential diagnostic and prognostic markers for lung cancer, which may provide more accurate prognostic indicators for lung cancer." (PMID 35346237, 2022). "Specifically, the high expression of STEAP1 in patients with stage I lung cancer was associated with poor prognosis, and the low expression of STEAP2 in patients with stage I lung cancer was associated with poor prognosis, both of which were statistically significant (P < 0.05)." (PMID 35346237, 2022). "The results of previous studies and the analysis results of this study suggest that STEAP1 and STEAP2 may be potential diagnostic markers of lung cancer, which can provide a basis for the prognostic assessment of lung cancer." (PMID 35346237, 2022). "We adopted bioinformatics methods to systematically and comprehensively analyze the expression level and possible prognosis of STEAP1 and STEAP2 in lung cancer." (PMID 35346237, 2022). "We also compared STEAP1 and STEAP2 transcriptional levels between lung cancer and normal tissues using GEPIA." (PMID 35346237, 2022). "The purpose of this study was to evaluate the expression and prognostic value of STEAP1 and STEAP2 in patients with lung cancer." (PMID 35346237, 2022). "Real-time quantitative polymerase chain reaction, western blotting, and immunocytochemistry were used to evaluate the expression of STEAP1 and STEAP2 in three lung cancer cell lines and normal lung epithelial cell lines." (PMID 35346237, 2022). "The KM curve showed that the downregulation of STEAP1 expression and upregulation of STEAP2 expression were related to a good lung cancer prognosis." (PMID 35346237, 2022).
lung carcinoma (continued). "In summary, this study focused on the expression of STEAP1 and STEAP2 in lung cancer and evaluated their clinical and prognostic value." (PMID 35346237, 2022). "Analysis of the Oncomine database and GEPIA showed that STEAP1 was upregulated and STEAP2 was downregulated in lung cancer tissue, and both expressions were related to the clinical stage of lung cancer." (PMID 35346237, 2022). "The expression of STEAP1 and STEAP2 in lung cancer cells was consistent with that in tissues." (PMID 35346237, 2022). "In addition, we used GEPIA to analyze the relationship between STEAP1 and STEAP2 mRNA levels and lung cancer staging." (PMID 35346237, 2022). "Therefore, the purpose of this study was to investigate the expression of STEAP1 and STEAP2 and their potential prognostic value in order to provide a basis for new strategies for the treatment of lung cancer." (PMID 35346237, 2022). "However, at present, there are relatively many studies on the role of STEAP1 in the occurrence and development of cancer, but the pathogenesis of STEAP2 in lung cancer is still unclear." (PMID 35346237, 2022). "However, the current research on STEAP2 is still in the preliminary stage, and few studies have focused on the prognostic value of STEAP1 and STEAP2 in lung cancer." (PMID 35346237, 2022). "However, there are some gaps in our research; as such, more studies are needed to elucidate the molecular mechanisms of STEAP1 and STEAP2 in lung cancer." (PMID 35346237, 2022). "Therefore, our controversial result that STEAP1 is negatively correlated with STEAP2 expression level in lung cancer may not be a “real” controversy, and further studies are still needed to clarify." (PMID 35346237, 2022). "The expression and prognosis of STEAP1 and STEAP2 in patients with stage II and III lung cancer were not statistically significant (P >0.05)." (PMID 35346237, 2022).
ovarian carcinoma (6 papers, 2016 to 2025). A malignant neoplasm originating from the surface ovarian epithelium. "The STEAP1 protein is overexpressed in prostate, bladder, renal, breast, testicular, pancreatic, cervical, and ovarian cancer, making STEAP1 an attractive candidate for a wide range of cancer immunotherapies." (PMID 34358202, 2021).
prostate tumors (6 papers, 2012 to 2025). "When connexins that are strongly associated with prostate tumor growth (e.g., connexin 43 and connexin 32) are inhibited, intercellular communication shifts to STEAP1-mediated communication." (PMID 36011027, 2022). "Here we show that collagen-binding domain-fused IL-12 (CBD-IL-12) secreted from CAR-T cells to target human six transmembrane epithelial antigen of prostate 1 (STEAP1) is retained within murine prostate tumours." (PMID 41125870, 2025). "STEAP1 overexpression promotes prostate tumor growth, and STEAP1 knockdown decreases prostate tumor growth." (PMID 36011027, 2022).
colon cancer (5 papers, 2020 to 2025). "STEAP1 is overexpressed in several types of cancer, including prostate, bladder, and colon cancer, making it a potential biomarker for these diseases." (PMID 39842382, 2025). "STEAP1 was up-regulated in the colon cancer cells with STAT3del compared to those with the wild type STAT3." (PMID 33535185, 2021). "Moreover, STEAP1 is highly expressed in multiple cancer tissues such as prostate, bladder, ovarian, and colon cancer and has the role of promoting invasion of tumor cells." (PMID 38191397, 2024). "Moreover, STEAP1 is highly expressed in multiple cancer tissues such as bladder, colon cancer, ovarian, and prostate and has the role of promoting invasion of tumor cells." (PMID 35313641, 2022).